FSTL1 (follistatin like 1)
Diseases named in the same sentence as FSTL1 in open-access papers (continued):
Sharing a sentence is not in itself a finding about the gene and the disease.
tumor (continued). "The activated MSCs robustly support tumor progression and metastasis directly by inducing EMT, and indirectly through the production of numerous immunomodulatory molecules, such as TGFβ, PGE2, IL6, IL8, VEGF, TNFα, IL1β, IDO, and FSTL1, to generate and expand Tregs, MDSCs, and DCregs." (PMID 33535613, 2021). "Snail-induced FSTL1 directly damages CTL induction, and indirectly through the induction of pluripotent mesenchymal stem/stromal cells (MSCs), which not only generate dysfunctional CD8low CTLs via ALCAM signaling but also further promote tumor metastasis, especially to the bone marrow." (PMID 33535613, 2021). "Co-expression genes of FSTL1 were enriched in extracellular region/exosome/space/matrix/matrix organization, cell adhesion, and pathway in cancer, focal adhesion, PI3K-Akt signaling pathway, ECM-receptor interaction, which have been proved correlated with tumor development and tumor immunity." (PMID 33292276, 2020). "Bioluminescence images and IHC also revealed that Fstl1 silencing could not affect the tumor growth and the levels of cleaved caspase-3, γ-H2AX, and MGMT in DIP2A-KD P-GBM2 cells following TMZ treatment." (PMID 30542120, 2019). "A 100% tumor formation rate suggested that FSTL1 does not affect tumor incidence in vivo." (PMID 26918942, 2016). "However, FSTL1+ tumor cells, which were most abundant in the PD-1+SMI group, expressed high levels of the lung CSCs marker genes CD44 and ALCAM, and the CSCs score was significantly higher than those in the other subclusters, except for NEAT1+ and XIST+ tumor cells." (PMID 37430270, 2023). "However, the regulation of FSTL1 expression in human tumours had hitherto not fully elucidated." (PMID 29844309, 2018). "In addition, we immunohistochemically analyzed tumor tissues of advanced breast cancer patients, and found that accumulation of ALCAM+ cells (possibly including the sMSCs) significantly correlates with FSTL1 expression level in tumor portions, but not in the adjacent normal counterparts." (PMID 25883937, 2015).
cancer (59 papers, 2015 to 2025). A tumor composed of atypical neoplastic, often pleomorphic cells that invade other tissues. "FSTL1 is widely known as an inflammatory and pathogenic molecule associated with many diseases, such as rheumatoid arthritis, obesity, and cancer." (PMID 33535613, 2021). "It has been reported that cancer-associated fibroblasts upregulate the expression of NCOA4 in NK cells through the DIP2A-P38 pathway via a mechanism driven by cancer-associated fibroblast-derived FSTL1, leading to ferritinophagy and ferroptosis in NK cells." (PMID 40959272, 2025). "FSTL1 encodes for a small glycoprotein secreted by skeletal muscle and myocardium and have been implicated in various physiological and pathological processes, including inflammation, wound healing, and cancer progression." (PMID 40558566, 2025). "The role of FSTL1 in cancer is complex because of the diversity of FSTL1‐producing cells, receptors, and intracellular signals." (PMID 39804150, 2025). "Proteins such as GDF15, MERTK, MRP2, SMPD-1, GPNMB, GRN, and FSTL1, while less widely recognized, have emerging roles in cancer progression, immune modulation, and metabolic regulation." (PMID 40805206, 2025). "Several studies have shown that FSTL1 is involved in systemic autoimmune disease, developmental processes, cardiovascular diseases, and cancer." (PMID 39804150, 2025). "According to previous studies, FSTL1 activates the Wnt/β-catenin pathway, which is involved in tumorigenesis and cancer stem cell maintenance." (PMID 38672212, 2024). "Briefly, FSTL1 overexpression stimulates the Wnt/β-catenin pathway to induce tumorigenesis and cancer stem cell maintenance and inhibits the BMP2 pathway, which results in the undifferentiation of cancer cells." (PMID 38672212, 2024). "The genes COL1A2, FSTL1, LUM, and SPARC encode proteins that structurally compose the ECM and that are frequently altered in cancer, conferring a poor prognosis and invasive phenotypes." (PMID 39563861, 2024). "On the other hand, claudin-1 upregulation exhibits potential anti-metastatic and anti-cancer effects in ATC (FSTL1) and FTC (dexamethasone)." (PMID 39458944, 2024). "Despite these significant findings in other cancer types, the exploration of FSTL1 in cSCC remains largely uncharted." (PMID 38605354, 2024). "All myokines identified in our study as potentially associated with cancer cachexia are normally released by various cells, predominantly within the immune system (IL-6, IL−8, FABP3) and adipose tissue (leptin, FSTL-1)." (PMID 39411315, 2024). "Follistatin-like 1 (FSTL1) is a cancer-related matricellular secretory protein with contradictory organ-specific roles." (PMID 36756161, 2023). "As a pro-inflammatory factor, Follistatin-like 1 (FSTL1) has been reported to promote various cancers malignant progression." (PMID 37007125, 2023). "Based on the RT-qPCR results of FSTL1 gene expression, there was an overall decrease in the mRNA expression of FSTL1 in cancer tissues compared to their adjacent normal tissues." (PMID 35450397, 2022). "Some studies demonstrated that FSTL1 as a critical effector molecule in cancer progression via affecting host immunity." (PMID 33639614, 2021). "We found that expression of miR-198 and FSTL1 was unrelated or even inversely correlated in all cancer types." (PMID 34572448, 2021). "For example, miR-198 is embedded in the 3′ untranslated region (exon 11) of FSTL1 and their expression was unrelated, or even inversely correlated in all cancer types." (PMID 34572448, 2021). "The potential functions and mechanisms of FSTL1 in cancer progression and immunology need to be discovered." (PMID 33292276, 2020). "To further understand the effect of FSTL1 in the prognosis of GC, we studied the relationship between FSTL1 expression and the clinicopathological features of these cancers using the Kaplan-Meier plotter database and immunohistochemistry assay." (PMID 33292276, 2020).
cancer (continued). "TIMER and Oncomine databases were used to assess the differential expression of FSTL1 based on cancer type." (PMID 33292276, 2020). "Altered expression of FSTL1 has been described in malignancies, even though its contribution to carcinogenesis remains controversial as FSTL1 can either positively or negatively regulate cancer cell growth and survival." (PMID 30131854, 2018). "During cancer metastasis from the primary site to the bone, FSTL1 mediates cancer cell invasion and expands a population of bone marrow-derived pluripotent mesenchymal stem-like cells." (PMID 29357946, 2018). "FSTL1 was positive in 65.2% (58/89) of ccRCC tissues and 94.0% (63/67) of the adjacent non-cancer tissues." (PMID 29357946, 2018). "Immunoistochemical analysis of colonic sections showed that both cancer cells and lamina propria mononuclear cells express FSTL1." (PMID 30131854, 2018). "In colorectal cancer (CRC), FSTL1 is selectively expressed in cancer stroma and attenuates CRC cell proliferation." (PMID 29357946, 2018). "Both EMILIN1 and FSTL1 exert contrasting effects in different types of cancer probably because both interact with TGF-β which is a paradigm of duality in cancer (Massagué, 2008)." (PMID 29740513, 2018). "These research results again implicate that the function of FSTL1 is different in different cancer types." (PMID 28852126, 2017). "For example, FSTL4 (a member of the follistatin-like proteins; FSTl1 instead of FSTL4) was identified as candidate gene affected by LOH in a murine cancer model." (PMID 27159447, 2016). "Leveraging these properties, our study suggests that the FSTL1-targeting drug or ASO for THOC7-AS1/OCT1/FSTL1 axis could be labeled or delivered using nanosilver particles, which may enhance their anti-cancer effects." (PMID 38605354, 2024). "Functional targeting of cancer-associated fibroblasts (CAFs) using a combination of DFO and follistatin-like protein 1 (FSTL1) -neutralizing antibody significantly alleviated CAF-induced natural killer cell (NK cell) ferroptosis and boosted the cytotoxicity of NK cells against GC." (PMID 39622791, 2024). "Therefore, the effect and mechanism of FSTL1 in cancer progression remain to be explored to a large extent." (PMID 36756161, 2023). "More specifically, therapeutic modulation of FN1, TPT1, RTN4, and FSTL1, for which knockdown has been shown to result in reduced cell proliferation and migration in cancer cells, may represent new potential therapeutic avenues for pterygia as well." (PMID 35174178, 2021). "However, results from cancer progression studies of the proliferative, apoptotic, migratory, and inflammatory effects of FSTL1 were inconsistent." (PMID 32050622, 2020). "Interestingly, the expression of FSTL1 changes with respect to its level and pattern during various diseases, including cardiovascular disease, cancer progression, and systemic autoimmune diseases." (PMID 29594389, 2018). "First, the cancer inhibition effect of FSTL1 was investigated only in vitro." (PMID 29357946, 2018). "There is controversy about the roles of EMILIN1 and FSTL1 in cancer." (PMID 29740513, 2018). "In prostate cancer, the androgen-dependent up-regulation of FSTL1 promotes growth of cancer cells." (PMID 29357946, 2018). "The similarities in keratinocyte behavior between wound healing and epithelial carcinoma led us to hypothesize that the miR-198/FSTL1 switch might be involved in progressive HNSCC." (PMID 28827448, 2017). "However, the functional mechanism of FSTL1 in cancer is poorly characterized, and its proliferative effects are ambiguous." (PMID 26716515, 2016). "In cancer metastatic to bone, FSTL1 can mediate cancer cell invasion." (PMID 27225192, 2016). "Epigenetic downregulation of FSTL1 might lead to the proliferation and migration of cancer cells and inhibit the function of surrounding macrophages." (PMID 26918942, 2016). "Due to its multiple functions, defining the role of FSTL1 in cancer has been a challenge." (PMID 26716515, 2016).
cancer (continued). "We hypothesized that promoter hypermethylation in NPC cells might inhibit the paracrine effects of FSTL1 secretion and thus block the cancer–stromal interaction, thereby allowing NPC cells to escape an attack of stromal immune cells." (PMID 26918942, 2016). "Thus, we speculated that FSTL1 might affect the proliferation of metastatic cancer cells by altering the lung TME, which might be a critical cause of this phenotype." (PMID 37238210, 2023). "However, the role of FSTL1 in cancer has been controversial." (PMID 35805015, 2022). "However, 3 cancer tissues presented higher FSTL1 expression." (PMID 35450397, 2022). "Hypermethylation of FST/FSTL1 could directly impair this restraint, leading to cancer progression." (PMID 26664652, 2015). "Clinically, FSTL1 is primarily expressed in HCC CAFs and correlates with advanced cancer stage, reiterating its importance in HCC progression." (PMID 36708970, 2023). "FSTL1 and HGF independently promote HCC metastatic dissemination, a phenotype that can be attributed to stemness acquisition in cancer cells." (PMID 36708970, 2023). "The carcinogenesis of FSTL1 (previously named TSC-36) was first discovered when researchers found that FSTL1 was reduced and even undetectable in various v-myc/v-ras-transformed cells and human cancer cells." (PMID 36756161, 2023). "Many of the top overexpressed (e.g., FSTL1, TNS1, DDR2, or VWF) or underexpressed genes were suggested to promote invasion and/or metastasis in different cancer types." (PMID 36359790, 2022). "As secreted follistatin-module-containing glycoproteins, several FSLT members, covering FSTL1 and FSTL5, have been discovered to participate in cancer cell growth, stemness, chemoresistance, invasion, and migration." (PMID 34555811, 2021). "Moreover, FSTL1 is considered a determinant of immune dysfunction mediated by mesenchymal stroma/stem cells (MSCs) and immunoregulatory cells, and may therefore represent a target to suppress cancer progression." (PMID 32695142, 2020). "Of these genes, RHOJ and FSTL1 have particularly been characterized more extensively, whereas ETV1 and HAS2 are newly emerging in the cancer literature." (PMID 31109321, 2019). "VIM was known as a potential cancer therapeutic target, and reports found that VIM could promote the invasion and metastasis of CRC cells by binding to overexpressed FSTL1." (PMID 40864806, 2025). "On the contrary, FSTL1 suppresses the BMP2 pathway, which induces cancer cell differentiation." (PMID 38672212, 2024). "Similarly, the expression of SLC3A2, TUBA1B, TUBA1C, TUBB, FSTL1, and INSIG1 was affected by FIRΔexon2, suggesting that FIR and FIRΔexon2 engage in the transcription of various cancer-related mRNAs." (PMID 38139171, 2023). "Interestingly, 7 of the top 10 oncogene candidate protein-coding genes identified (e.g., FSTL1, VCAM1, VWF) were shown in other cancer types to promote cell migration, invasion, or metastasis." (PMID 36359790, 2022). "In ccRCC tissues, FSTL1 was negative or detected in the cytoplasm of cancer cells; HIF-1α and HIF-2α were positive in 52.9% (45/85) and 66.7% (52/78) of ccRCC cases, respectively." (PMID 29357946, 2018). "Same prognostic trends and positive correlation between the expression levels of FSTL1, BMP4, p-Smad1/5/8, and Smad4 indicates FSTL1 may regulate cancer progression through BMP4-p-Smad1/5/8-Smad4 signaling." (PMID 28852126, 2017). "Therefore, we believe that FSTL1 knockdown may derepress NF-κB and HIF-2α signaling in ccRCC cells, thus promoting cancer invasion and metastasis." (PMID 29357946, 2018). "Although the effects of FSTL1 knockdown were not drastic, FSTL1 secretion may be one of the mechanisms by which TGF‐β1 stimulates cancer cluster attachment to the airway epithelium." (PMID 39804150, 2025).
cardiovascular diseases (15 papers, 2014 to 2026). "FSTL1 is a secreted glycoprotein and has previously been implicated to be a potential prognostic marker for cardiovascular diseases." (PMID 41068431, 2025). "Many of the functions of FSTL1 in cardiovascular diseases are associated with its roles in cardiomyocytes and vascular cells." (PMID 41068431, 2025). "In cardiovascular diseases, FSTL1 has been implicated in the activation of the PI3K/Akt signaling, exhibiting protective effects." (PMID 33509151, 2021). "It is still unknown whether a high plasma FSTL1 concentration simply reflects underlying disease processes or has a maladaptive and/or compensatory role in modulating the pathogenesis of cardiac dysfunction in patients with cardiovascular disease." (PMID 31034503, 2019). "While studies on FSTL1 in cardiovascular diseases are limited, other pathological conditions have provided useful insights." (PMID 41602834, 2026). "Many recent studies indicated that FSTL1 not only serves as a molecular marker but also possesses important functions in the development of cardiovascular diseases." (PMID 41068431, 2025). "The function of FSTL1 in the cardiovascular system seems to be poorly understood in patients with cardiovascular disease." (PMID 31034503, 2019). "Follistatin-like 1 (Fstl1) is a circulating glycoprotein that plays a crucial role in cardiovascular diseases and inflammation-related disorders." (PMID 27145224, 2016). "FSTL1 can serve as a useful biomarker of cardiovascular disease given that elevated circulating levels of FSTL1 are found in patients with ACS and associated with chronic HF." (PMID 25171167, 2014). "During the development of cardiovascular diseases, the expression of FSTL1 is closely related to cardiovascular pathology; therefore, an in-depth understanding of its biological functions is important for the treatment and prevention of cardiovascular diseases." (PMID 41602834, 2026). "FSTL1 has a broad range of physiological functions, including regulating endothelial cells’ activity, promoting revascularization and modulating metabolic pathways in cardiovascular disorders." (PMID 41458545, 2025). "The product is a secreted glycoprotein, FSTL1 with activities in angiogenesis, cell proliferation, differentiation, embryogenesis, metastasis, and wound healing; specifically reducing inflammation and fibrosis in cardiovascular disease." (PMID 38861581, 2024). "A report that plasma FSTL1 levels were correlated with hsCRP and ROMs in healthy Japanese male subjects suggests that FSTL1 may be a biomarker of metabolic dysfunction and cardiovascular disease." (PMID 31034503, 2019). "Thus, circulating levels of Fstl1 could be a useful biomarker of metabolic dysfunction and cardiovascular disease." (PMID 27145224, 2016).
infection (7 papers, 2014 to 2025). The state of being infected such as from the introduction of a foreign agent such as serum, vaccine, antigenic substance or organism. "Therefore, we speculate that FSTL1 is closely associated with the etiology of infection and regulation of inflammation in AS, revealing a potential pathogenic mechanism and therapeutic target for AS." (PMID 37322475, 2023). "In this study, we first found that infection with PEDV enhanced the FSTL1 expression through the transcription factor KLF5." (PMID 39670742, 2025). "In this study, we attempt to investigate whether FSTL1 and TLR4 are implicated in the host cell entry and infection by PEDV." (PMID 39670742, 2025). "AAV9 infection induced a 2.5-fold increase in FSTL1 expression in the heart." (PMID 32831995, 2020).
immune diseases (3 papers, 2015 to 2025). "In immune diseases, FSTL1 has a dual function during inflammatory process (anti-inflammatory factor in the acute phase, then pro-inflammatory effect in chronic diseases), probably due to the activation of different signalling pathways." (PMID 40558566, 2025). "As a secreted extracellular glycoprotein, FSTL1 is widely considered to participate in development and immune diseases pathogenesis." (PMID 25888873, 2015).
adenocarcinoma (2 papers, 2017 to 2020). A common cancer characterized by the presence of malignant glandular cells. "The results indicated that there were significant positive correlations among FSTL1, BMP4, Smad4, and p-Smad1/5/8 IHC expression in adenocarcinoma." (PMID 28852126, 2017).
cardiac disease (2 papers, 2020 to 2025). "Another myokine of importance for cardiac disease is follistatin-like 1 (FSTL1), which is expressed by skeletal as well as cardiac muscle cells." (PMID 33013484, 2020).
respiratory diseases (2 papers, 2021). "There is growing evidence that FSTL1 plays an important role in respiratory diseases." (PMID 33509151, 2021).
diseases of the musculoskeletal system (1 paper, 2019). "The expression of follistatin‐like protein 1 (FSTL1) is closely associated with diseases of the musculoskeletal system." (PMID 30644158, 2019).
psychiatric disorder (1 paper, 2018). A disorder characterized by behavioral and/or psychological abnormalities, often accompanied by physical symptoms. "Taken together with our present findings, it is possible that Fstl1 may play a role in the pathophysiology of psychiatric disorders on downstream of Ifitm3." (PMID 30348171, 2018).
renal diseases (1 paper, 2021). "Furthermore, FSTL1 is involved in the activation of the AMPK signaling pathway in cardiac and renal diseases." (PMID 33509151, 2021).